APOE (apolipoprotein E)
Diseases named in the same sentence as APOE in open-access papers (continued):
Sharing a sentence is not in itself a finding about the gene and the disease.
tumor (continued). "In conclusion, the two prognosis-related genes APOE and CTSD were mainly related to regulating tumor and metabolism-related functions." (PMID 34873574, 2021). "As for exosomes derived from immune cells, TAMs with M2 phenotype transfer apolipoprotein E (ApoE) by exosomes to trigger the activation of PI3K–Akt signaling pathway in GC cells and subsequently aggregate tumor cells’ migration." (PMID 34268118, 2021). "Using multiplexed immunohistochemistry, C1Q+TREM-2+ TAMs were found to be tumor-specific and C1Q+TREM-2+APOE+ TAMs located significantly nearer the tumor cells than triple-negative TAMs." (PMID 34831009, 2021). "At the same time, the presence of cell migration inhibitors (APOE, AKT1, BARD1, GDF2) in exosomes from blood HFs accompanied by low stimulating effects on the migration velocity of tumor cells." (PMID 32218180, 2020). "Endogenic apoE combines with LRP1 and LRP8 receptors in cancer cells and endothelial cells, respectively, which not only hinders tumor cell invasion and metastasis but also restricts the recruitment of epithelium." (PMID 32306242, 2020). "APOE activated the PI3K/AKT/mTOR signaling pathway and played an important regulatory role in angiogenesis, tumor cell growth, and metastasis." (PMID 33015179, 2020). "Western blot and immunohistochemistry analysis demonstrated that TREM-1 is up-regulated in ApoE KO mice in both urethane-induced lung tumor and B16F10 lung metastasis tumor tissues." (PMID 31275318, 2019). "These facts accord with our results revealing that ApoE KO mice showed more infiltrated CD57+ NK cells and CD8α+ T cells at tumor tissues compared to WT mice." (PMID 31275318, 2019). "The regulator of synaptogenesis, APOE, was found to be up-regulated in the GBM50 and GBM3 tumours, but down-regulated in the GBM0.2 tumours and the mtDNA-depleted cells." (PMID 30208958, 2018). "In contrast, while the lipoprotein transporter APOE was variably regulated by density across cell lines, the cholesterol efflux pump ABCA1 was significantly upregulated in both the normal and tumor lines at high densities." (PMID 28118603, 2017). "Besides its well-recognized role in lipid metabolism, ApoE has been shown to be involved in several pathophysiological processes, including antioxidant and immune activities, as well as a modulating effect on angiogenesis, tumor cell growth and metastasis induction." (PMID 23098561, 2012). "The distribution patterns of LAD-loaded apoE liposomes and native LDL in the tumour-bearing mice were very similar, which supports the role of the LDL receptor in the disposition of the prodrug-loaded particles." (PMID 9862571, 1998). "By analyzing the ligands corresponding to chemokine target genes expressed in immune cells, we found that the chemotactic response of immune cells was mediated by the expression of NRG1 and HMGB1 ligands on Tum_1 tumor cells, which interacted with the CXCL1 target on APOE+ macrophages." (PMID 40470730, 2025). "APOE may influence T cell function by modulating lipid metabolism and immune regulation, while LAMB3 may participate in tumor immune responses by affecting T cell migration and localization." (PMID 41343534, 2025). "In ovarian cancer (OC) and melanoma, ApoE binds LRP8 on MDSCs, enhancing anti-tumor immunity." (PMID 40607438, 2025). "Additionally, Macro_APOE proportion significantly increased in tumor samples, which was consistent with the IHC analysis that APOE was highly expressed in AEG tumor tissue compared to NAT in the validate cohort." (PMID 40963562, 2025).
tumor (continued). "In the 4 T1 murine BC model, combined APOE inhibitor and ICI therapy exhibited optimal anti‐tumor effects, suggesting that targeting APOE+ macrophages could potentially enhance the therapeutic efficacy of ICIs." (PMID 40356222, 2025). "In our integrated analysis, we discovered a unique subpopulation of tumor cells (MP3 cluster) in D‐TGCT that could regulate differentiation of CD34+ Fbs into MMP3+ Fbs and APOE+ Fbs through the COL6A3 − (ITGAV + ITGB8) ligand–receptor pair." (PMID 40126353, 2025). "Moreover, APOE promotes tumor growth and proliferation in PTC through glycolysis, and analysis has shown that the FTO/APOE axis inhibits PTC glycolysis by modulating the IL-6/JAK2/STAT3 signaling pathway." (PMID 40819127, 2025). "Furthermore, SPP1-based co-culture experiments combined with Western blot, ELISA, and flow cytometry demonstrated that tumor-derived SPP1 regulates macrophage phenotypes and contributes to the immunosuppressive function of APOE+ macrophages." (PMID 40303328, 2025). "Furthermore, both APOE+ and SPP1+ macrophages showed a marked preference for the resistant tumor microenvironment." (PMID 40303328, 2025). "Notably, CD14+APOE+ cells were predominantly located in areas with high MMP7+ tumour cells, suggesting a strong co‐localisation pattern between MMP7+ tumour cells and CD14+APOE+ cells." (PMID 39187937, 2024). "However, a bright red fluorescence was seen in the tumor tissues of mice treated with ANC@RNP, again demonstrating the significance of ApoE‐functionalization in mediating BBB permeability and GBM targeting." (PMID 38943253, 2024). "In addition, our investigation revealed the geographical co‐localisation of CD14+APOE+ cells and MMP7+ tumour cells, and examined the intercellular communication between these two cell types." (PMID 39187937, 2024). "We verified this by plotting the CTHRC1+GREM1+ myCAF, SPP1+APOE+ TAM, and EMT signatures from previous parts of our study, which showed clear overlays, supporting the co-localization of fibroblasts and macrophages while promoting the pro-tumor TME." (PMID 39075108, 2024). "Additionally, the KLF2 maintaining tumour cells survival, exhibited heightened regulon activities in CD14+APOE+ cells." (PMID 39187937, 2024). "Subsequently, we examined the clinical importance of MMP7+ tumour cells and CD14+APOE+ cells." (PMID 39187937, 2024). "This spatial proximity suggests a potential interaction where APOE+ TAMs may contribute to the upregulation of MMP7 in cancer cells, thereby facilitating tumour invasion and metastasis." (PMID 39187937, 2024). "In summary, while our study offers significant insights into the spatial structure and functional characteristics of CD14+APOE+ cells and MMP7+ tumour cells in NSCLC, additional research is needed to address these limitations and to further elucidate the mechanisms underlying therapy resistance." (PMID 39187937, 2024). "Besides, significantly positive correlation between APOC1+APOE+ macrophages and CD163+ macrophages were analyzed in tumor nest." (PMID 36709495, 2023). "Apolipoprotein-E (APOE) and transforming growth factor (TGF)-β1 were identified as important ligands that interact between stromal cells and tumor epithelial cells and could be potential therapeutic targets for both AC and MC." (PMID 37091868, 2023). "LXR treatment failed to significantly reduce the number of tumour MDSCs or tumour volume in ApoE−/− mice without ApoE B16F10 tumour cells compared with WT mice." (PMID 37261073, 2023). "Among them CCNB1, MIF, PLA2G4A may be regarded as oncogenes, whereas RNASE3, APOE, FOXO1, KIT, and EGR1 may be tumor suppressor genes." (PMID 37065484, 2023). "This study demonstrated that constitutive lack of APOE or APOE inhibitor treatment curbed tumor growth.This is not the first time it has been reported in cancer." (PMID 36147474, 2022).
tumor (continued). "Along with TREM2, these cells were enriched for genes involved in lipid metabolism (APOE), immunosuppression (MARCO, CD163, CD81), and the complement cascade (C1QB), suggesting that TREM2 specifically marks a subset of tumor-specific immunosuppressive macrophages." (PMID 35746551, 2022). "C4 TAMs (964 cells in residual tumor) express SPP1, TREM2 and APOE." (PMID 35784460, 2022). "By ligand and receptor analysis, we observed TASCs, Mφ_APOE and LAMP3+ DCs, as the key mediators in complex intercellular networks of interaction, orchestrated the immunosuppressive microenvironment and promoted tumor progression." (PMID 35999201, 2022). "Individuals carrying ε4 are at a higher risk of tumor with or without CVD, and APOE polymorphisms affect the serum lipid profiles." (PMID 36057714, 2022). "Due to the lower expression of ApoE, the upregulation of TREM-1 can be induced by the high expression of T-bet, which is involved in the secretion of IFN-γ, perforin, and granzyme to enhance the anti-tumor cytotoxicity mediated by NK cells." (PMID 36506554, 2022). "Results show remarkable suppression of tumor growth when ApoE is absent from the system with significant tumor elimination when compared with WT controls." (PMID 36341364, 2022). "Macrophage in this cluster had high expression of type I interferon signaling related genes (IFITM3, IFI27, MX1, IFI6, and ISG15) as well as gene features related to immunosuppressive phenotype (APOE, APOC1, S100A9, and GPNMB), whereby participating in tumor immune regulation." (PMID 35265520, 2022). "First, we did not use myeloid specific APOE knockout mice to further verify the mechanism of APOE action in mouse tumor macrophages, because the culture time of knockout mice is too long." (PMID 36147474, 2022). "Moreover, treatment by exploiting APOE inhibitor (COG 133TFA, αAPOE) was capable of curbing tumor development and fostering regression if in combination of αPD-1." (PMID 36147474, 2022). "ApoE in tumor cells or endogenously produced in the mice was capable of suppressing tumor immunity and significant tumor immunity only occurred when ApoE was absent from both tumor cells and the murine host." (PMID 36341364, 2022). "The observations from our mouse model imply that the absence of tumor ApoE alone is not sufficient to induce immunity in that the serum level of the host also has significant suppressive effects on induced immunity." (PMID 36341364, 2022). "Decreases in APOE in patients with early-stage CRC (0.58-fold) and late-stage CRC (0.68-fold) in this study indicated that APOE may play roles in suppressing tumor activity, which is consistent with previous studies." (PMID 34063271, 2021). "The correlation analysis of the expression of GSTA2 and the identified ROS-associated genes using the LIHC database in the GEPIA web server revealed that the expression level of GSTA2 was significantly correlated with ALB, TPO, APOE, MBL2, and FTH1 in the tumor tissues." (PMID 34290233, 2021). "It is found that APOE and CTSD play an essential role in many aspects of the tumor, such as cell adhesion, the effect of ROS, the regulation of oxidative stress, fat metabolism, and the regulation of tumor tissue." (PMID 34873574, 2021). "Scavenger receptor BI, proprotein convertase subtilisin/kexin type 9 (PCSK9), apoE and apoAII were similar in tumor and non-tumor tissues." (PMID 34629057, 2021). "Treatment with LXR agonists leads to apoptosis of MDSCs and a reduction in tumor volume, resulting from activated transcription target apolipoprotein E (ApoE), which binds with its receptor, expressed on MDSCs, and induces MDSC depletion, ultimately inhibiting tumor growth." (PMID 32325683, 2020). "Moreover, ApoE−/− as compared with WT mice exhibited reduced survival when receiving GL261 LD+ cells, suggesting that combined tumor cell lipid loading and systemic lipid levels has a significant impact on GBM aggressiveness." (PMID 31174567, 2019).
tumor (continued). "Even though the significant role of ApoE in cholesterol homeostasis and the significance of cholesterol in tumor growth are well-known, the role and mechanism of ApoE in tumor cell growth are not clear." (PMID 31275318, 2019). "Meanwhile, the level of ApoE expression in stage II tumor sample which had no progression evidence in 5 years was lower than that in PC of synchronous liver metastases." (PMID 30631342, 2018). "Likewise, the regulator of synaptogenesis, APOE, was up-regulated in the GBM50 and GBM3 tumours but down-regulated in the mtDNA-depleted cells." (PMID 30208958, 2018). "At the same time, ApoE could activate PI3K/AKT/mTOR signaling pathway, which has been confirmed as a critical regulator during tumor progression, including cell–cell adhesion, proliferation, and migration." (PMID 30631342, 2018). "TFF2 upregulated ApoE but ApoE−/−/CD2–Tff2 mice did not develop significantly more tumours than CD2–Tff2 mice, suggesting some functional redundancy within this system." (PMID 26841680, 2016). "Recent studies indicated that APOE may show its activity in CRC development by function in β-catenin localisation, tumor cell metastasis, DNA synthesis, antioxidant abilities, cell proliferation, and angiogenesis." (PMID 25029444, 2014). "However, APOE appears to play a negative role in tumor immunotherapy with senescent therapy, which is often used to improve disease outcomes by reducing APOE expression or levels." (PMID 40292294, 2025). "Lastly, this study relies on static single-cell and spatial transcriptome data, which do not capture the dynamic changes occurring within the tumor microenvironment, thus limiting insights into the evolutionary trajectory of APOE+ macrophage before and after ICB treatment." (PMID 40303328, 2025). "Notably, APOE in the tumor microenvironment is not solely derived from tumor cells, and its target cells extend beyond tumor cells alone." (PMID 41390817, 2025). "Furthermore, flow cytometry analysis indicated that the lack of ApoE led to a decrease in positive immune cells and an increase in immunosuppressive cells within the tumour microenvironment." (PMID 40662483, 2025). "Moreover, we also found APOE+ macrophages were the largest source of TGF-β signaling in ICB-resistant group, which is known to play a central role in shaping an immunosuppressive microenvironment, further contributing to immune evasion and tumor progression." (PMID 40303328, 2025). "Furthermore, the CD46 pathway, which is linked to immunosuppression, showed stronger interactions between APOE‐negative tumour cells and immune cells, particularly at the lymph node metastasis site." (PMID 39810624, 2025). "These spatial data suggest that APOE‐negative tumour cells may promote tumour growth and invasion by creating an immunosuppressive microenvironment." (PMID 39810624, 2025). "Building on these findings, we postulate that the lack of ApoE might impair immune function, consequently diminishing the immunological activity of tumour‐infiltrating CD8 T cells." (PMID 40662483, 2025). "Lastly, while we used multiplex immunofluorescence to validate the presence of CD14+APOE+ cells and MMP7+ tumour cells, additional validation using other complementary techniques such as flow cytometry or single‐cell RNA sequencing could provide a more robust confirmation of our findings." (PMID 39187937, 2024). "Moreover, pathway analysis revealed that SPP1+APOE+ TAM were regulated by the HIF-1 signaling pathway, inducing expression of VEGFA, LDHA, and ALDOA46,47, which not only promotes hypoxia but is another approach to induce EMT in tumor cells." (PMID 39075108, 2024). "Notably, APOE was also differentially expressed in post-infection convalescence and mid-infection of hematological tumor patients but not in non-tumor individuals." (PMID 38752789, 2024). "Moreover, APOE+ macrophages might function as an immune suppressive role in TME and promote the MVI of tumor cells." (PMID 37853415, 2023).
tumor (continued). "We further found that CXCL16 was highly expressed in Macro_APOE/CTSZ and CXCR6 was expressed in Treg, which might indicate that Macro_APOE/CTSZ utilized CXCL16 signals to recruit Treg cells to the tumor site, further exacerbating the immunosuppressive TME." (PMID 36587392, 2023). "Moreover, mIHC staining confirmed different expression levels of CD68+ &APOE+ macrophages, FOXP3+ &TNFRSF4+ Tregs, VEGFA, and TGFβ signaling between the tumor microenvironment of the de novo mild OLK and the OLK with moderate to severe dysplasia in clinical study." (PMID 36914617, 2023). "The findings of the current study showed that FTO inhibited expression of APOE through IGF2BP2-mediated m6A modification and may inhibit glycolytic metabolism in PTC by modulating IL-6/JAK2/STAT3 signaling pathway, thus abrogating tumor growth." (PMID 35090515, 2022). "To validate nanostring RNA transcript results in the apoE targeted group, we performed immunohistochemistry staining of the immune cell marker CD45 (lymphocyte common antigen) and CD3 (T cell marker) on the same tumor samples that we used for nanostring analysis." (PMID 36341364, 2022). "Compared to macrophages in the normal tissues, the TAMs have high expression of APOE (Fold change = 23.65909118, adjusted p value = 2.225074e−308) and SPP1 (Fold change = 17.40700342, adjusted p value = 2.225074e−308), which were reported to promote tumor cell growth and invasiveness." (PMID 33144684, 2021). "In accordance with our previous data, APOE, PMEL, QPCT, and SORT1 were specifically secreted in all metastatic tumor cell lines together with proteins involved in ECM deposition and adhesive proteins supporting the hypothesis of amyloid fibril deposition (Fig EV2F)." (PMID 32749065, 2020). "LXR agonist promotes the up-regulation of its transcription target ApoE, which binds to the LRP8 receptor on MDSCs, thus reducing the survival rate of MDSCs and increasing the CD8+ and CD4+ T cells activated by tumor invasion, reversing the tumor immune evasion, and promoting anti-tumor immunity." (PMID 33027968, 2020). "However, the specific role of ApoE related to anti-tumor activity of NK cells and Tc cells is not clear." (PMID 31275318, 2019). "Thus, our study identified a critical role of macrophage exosome-derived ApoE, but not endogenous ApoE in tumor cells, in mediating the crosstalk between TAMs and GC cells, promoting metastasis." (PMID 29567987, 2018). "Additionally, apoE genotypes do not appear to influence the survival time after surgical intervention, even when the analysis was restricted to the specific tumor histotypes." (PMID 23098561, 2012). "The APOE secretion by macrophages could not be directly confirmed within tumor core." (PMID 40745073, 2026). "SCGB1A1 and APOE may originate from stromal or immune cells rather than tumor epithelium." (PMID 41343534, 2025). "This posits that while apolipoprotein E may not directly affect the expression of the catalytic subunits of the proteasome, it could play a crucial role in the assembly or activation of the proteasome complex within the tumor microenvironment." (PMID 39456640, 2024). "APOE expression however appears to be independent of inflammatory phenotype in these tumors and may act as a separate and independent pathway in suppressing anti-tumor T-cell immunity." (PMID 36341364, 2022). "In addition, cell cycle distribution showed that WT conditioned media arrested activated T cells in the G0/G1 phase while apoE-/- conditioned media-maintained T-cells in the S and G2M phase of the cell cycle, similar to control media without prior exposure to tumor cells." (PMID 36341364, 2022).